DPP3 (dipeptidyl peptidase 3)
Diseases named in the same sentence as DPP3 in open-access papers (continued):
Sharing a sentence is not in itself a finding about the gene and the disease.
breast carcinoma (continued). "Data demonstrated that DPP3, DPP7, DPP8, DPP9, and DPP10 mostly had medium protein expression levels, while some clinical tissues showed strong positive expression levels of DPP3, DPP7, and DPP9 in breast cancer specimens." (PMID 34359286, 2021). "Based on these data, the authors proposed that DPP3 overexpression promotes breast cancer progression, metastasis and drug resistance, stabilizing NRF2, while the signature characterized by high levels of NRF2 and DPP3 might represent a potential biomarker for breast cancer prognosis and treatment." (PMID 33805996, 2021). "It was further observed that the involvement of DPP3 in NRF2 pathway induction is independent of its enzymatic activity and the interaction of DPP3 and KEAP1 is enhanced by oxidative stress in breast cancer cells." (PMID 37531267, 2023). "This family comprises seven members, including DPP3, DPP4, DPP6, DPP7, DPP8, DPP9, and DPP10; however, information on the involvement of DPPs in breast cancer is lacking in the literature." (PMID 34359286, 2021). "The Kaplan–Meier (KM) plot showed that high expression levels of DPP3 and DPP4 were correlated with poor survival of breast cancer patients, whereas other DPP family members were not." (PMID 34359286, 2021). "This study revealed that DPP3-FASN interaction might be a new therapeutic target and a novel prognostic biomarker for breast cancer." (PMID 38655619, 2024).
heart failure (8 papers, 2020 to 2025). Inability of the heart to pump blood at an adequate rate to meet tissue metabolic requirements. "High levels of circulating DPP3 (cDPP3) have been linked to the causes of cardiogenic shock, septic shock, acute coronary syndromes, heart failure, and serious viral diseases like COVID-19." (PMID 41226854, 2025). "Experimental and clinical evidence suggests that DPP3 plays an important role in the progression and prognosis of heart failure." (PMID 41226854, 2025). "And DPP3 plays an essential role in the pathogenesis of cardiovascular diseases such as hypertension and heart failure, which will contribute to its transformation from biomarker to therapeutic target." (PMID 36312232, 2022). "Given that elevated circulating Dpp3 is a known biomarker of adverse outcomes in heart failure, its reduction may reflect decreased cardiac stress and improved tissue homeostasis." (PMID 40724839, 2025).
Hypertension (8 papers, 2009 to 2025). The presence of chronic increased pressure in the systemic arterial system. "In 2016, Pang and colleagues showed that giving DPP3 to mice with angiotensin II–induced hypertension through their tails caused a big drop in blood pressure." (PMID 41226854, 2025). "A novel function of DPP3 and its potential therapeutic use in hypertension were revealed for the first time." (PMID 36312232, 2022). "In hypertension, animal models indicate that DPP3 might mitigate angiotensin II–induced vascular injury, suggesting a dual function as both a biomarker and a possible therapeutic target." (PMID 41226854, 2025). "It plays a vital role in regulating blood pressure in the rostral ventrolateral medulla, which suggests that DPP3 may play an important role in treating Parkinson's disease and hypertension, respectively." (PMID 36312232, 2022). "However, further studies are still required to verify whether DPP3 can be used as a biomarker of hypertension or participate in the occurrence and development of hypertension." (PMID 36312232, 2022).
Shock (7 papers, 2020 to 2025). The state in which profound and widespread reduction of effective tissue perfusion leads first to reversible, and then if prolonged, to irreversible cellular injury. "It has been shown that circulating DPP3 (cDPP3) plasma concentration increases in cardiogenic shock (CS) patients and correlates with high mortality risk." (PMID 37046568, 2023). "Increased circulating DPP3 concentrations were observed in patients with septic shock (54.6 [35–142.2] ng/mL) compared to the control group (13.7 [11.9–15.4] ng/mL, p < 0.001)." (PMID 40126750, 2025). "The presence and activity of DPP3 in plasma have recently been identified as a biomarker of adverse outcomes in patients suffering from cardiac shock, but it has also been detected in the plasma of healthy individuals." (PMID 37762480, 2023). "Although the mystery of DPP3 has been gradually unveiled, the results of animal experiments have shown that exogenous intravenous injection of DPP3 inhibitor procilizumab in cardiogenic shock improves cardiac function." (PMID 36312232, 2022). "However, the clinical value of these and other biomarkers, such as dipeptidyl peptidase-3 (DPP3, a biomarker of inflammatory and oxidative stress associated with decreased myocardial contractility) in cardiogenic shock, requires validation in larger studies." (PMID 41009628, 2025).
acute kidney injury (6 papers, 2020 to 2025). Sudden and sustained deterioration of the kidney function characterized by decreased glomerular filtration rate, increased serum creatinine or oliguria. "In cases of shock, dipeptidyl-peptidase 3, an enzyme involved in the degradation of angiotensin and opioid peptides, has been associated with acute kidney injury and mortality and preclinical studies have tested its neutralization." (PMID 37986086, 2023). "Persistently elevated levels of DPP3 were associated with acute kidney injury, worse total SOFA score at 48 h and worse outcomes, whereas early decline of DPP3 levels from high admission values towards normal values could predict improvement of organ function after 1 week." (PMID 40572747, 2025). "The secondary objective was to evaluate the association between DPP3 and organ dysfunction (i.e., circulatory failure and acute kidney injury (AKI))." (PMID 32321571, 2020). "DPP3 has been shown to predict primarily the development of acute kidney injury and the need for renal replacement therapy." (PMID 40572747, 2025). "When applying serial assessments of DPP3 levels, it was noted that patients who exhibited high DPP3 levels at 24 h were more likely to experience acute kidney injury and deterioration of their total SOFA score within 48 h." (PMID 40572747, 2025). "On the contrary, this was not the case for the association of DPP3 levels on day 1 with acute kidney injury, which remained significant in multivariate models even after adjusting for disease severity." (PMID 40572747, 2025). "Of note, DPP3 levels on days 2 and 3 provided additional predictive value for acute kidney injury to both SOFA and APACHE II scores, whereas DPP3 levels on day 1 added further predictive value only to APACHE II score." (PMID 40572747, 2025). "Indeed, baseline DPP3 levels were higher in patients with shock who developed acute kidney injury (22.7 [14.6–19.6] ng/mL) than in those who did not (16.5 [11.7–23.2] ng/mL)." (PMID 40572747, 2025).
colorectal cancer (5 papers, 2021 to 2025). A primary or metastatic malignant neoplasm that affects the colon or rectum. "What's more, accumulating evidences have demonstrated that the high expression of DPP3 was associated with the pathogenesis of cancers such as multiple myeloma, colorectal cancer, and ER-positive breast cancer." (PMID 36312232, 2022). "Recently, it was reported that DPP3 interacts with CDK1 protein in the colorectal cancer cell line and that DPP3 knockdown decreases proliferation, causes G2 arrest, promotes apoptosis, and inhibits cell migration." (PMID 37762480, 2023). "Studies have found that DPP3 can participate in protein turnover, oxidative stress, pain, ovarian cancer tissue invasiveness, colorectal cancer progression, the maintenance of bone homeostasis and inflammation." (PMID 36312232, 2022). "There are also reports on the overexpression and oncogenic functions of DPP3 related to poor survival in numerous other malignancies, including colorectal cancer, where DPP3 was found to target cyclin-dependent kinase 1 (CDK1), multiple myeloma, and esophageal carcinoma." (PMID 39941813, 2025).
COVID-19 (4 papers, 2023 to 2025). A disease caused by infection with severe acute respiratory syndrome coronavirus 2. "In the current study, DPP3 was elevated in both endpoints of the COVID-19 cohort, but in ROC analysis, bio-ADM and IL-6 each had a higher AUC than DPP3." (PMID 38336628, 2024). "Given that DPP3 can cleave RAS peptides and that Ang II levels were reported to be reduced in COVID-19 patients with ARDS compared to healthy controls, DPP3 was examined in a European multicenter prospective cohort study of 80 critically ill COVID-19 patients." (PMID 37986086, 2023). "In particular, patients with a negative PCR result for SARS-CoV-2 enabled comparison of the DPP3 levels to respiratory infections other than COVID-19." (PMID 37733154, 2023). "In non-COVID-19, DPP3 was significantly correlated with CRP (ρ = 0.35, p < 0.05), as opposed to IL-6 and leucocytes (each p = n.s)." (PMID 37733154, 2023). "However, only IL-6 showed a significant and stepwise increase between these subgroups in non-COVID-19 patients (each p < 0.05), opposite to DPP3 and leucocytes (each p = n.s)." (PMID 37733154, 2023). "So far, the existing data on the role of DPP3 in COVID-19 is restricted to critically ill patients." (PMID 37733154, 2023). "However, the existing data on the role of DPP3 in COVID-19 is restricted to critically ill patients." (PMID 37733154, 2023). "Particularly in COVID-19, DPP3 may be used as a complementary biomarker combining detection and prognostic value." (PMID 37733154, 2023). "DPP3 showed the potential to be a COVID-19-specific biomarker." (PMID 37733154, 2023). "Further studies will be needed to evaluate whether and how DPP3 might be involved in COVID-19 pathophysiology." (PMID 37733154, 2023). "In addition, the potential of DPP3 as a COVID-19 specific biomarker could be validated in conjunction with other established COVID-19 biomarkers in the future." (PMID 37733154, 2023). "Thus, ACE2 may be a link between SARS-CoV-2 and DPP3, implying that DPP3 might have a role in the pathophysiology of COVID-19." (PMID 37733154, 2023). "The aim of the present study was to examine whether Dipeptidyl-peptidase 3 (DPP3) and the inflammatory biomarkers IL-6, CRP, and leucocytes are associated with COVID-19 and able to predict the severity of pulmonary infiltrates in COVID-19 patients versus non-COVID-19 patients." (PMID 37733154, 2023). "DPP3, IL-6, CRP, and leucocytes were significantly elevated in COVID-19 patients with infiltrate above the median compared to patients with infiltrate below the median (each p < 0.05) and outpatients without imaging (each p < 0.05)." (PMID 37733154, 2023). "CRP, DPP3, and leucocytes were increased in COVID-19 patients with infiltrate above median (each p < 0.05, AUC: CRP 0.82, DPP3 0.70, leucocytes 0.67) compared to infiltrate below median, opposite to non-COVID-19 (each p = n.s)." (PMID 37733154, 2023). "DPP3 was significantly increased in COVID-19 patients compared to those without SARS-CoV-2 (p < 0.001), opposite to IL-6 and CRP (each p = n.s.)." (PMID 37733154, 2023).
endometrial cancer (3 papers, 2021 to 2025). Primary or metastatic malignant neoplasm involving the endometrium (mucous membrane that lines the endometrial cavity). "DPP3 is overexpressed in estrogen receptor-positive breast cancer and correlates with poor prognosis, and it is also more highly expressed in endometrial carcinomas vs. normal tissue." (PMID 33810334, 2021).
esophageal cancer (3 papers, 2023 to 2025). A primary or metastatic malignant neoplasm involving the esophagus. "In esophageal cancer, overexpression of DPP3 promotes tumor growth and indicates poor prognosis." (PMID 38655619, 2024).
multiple myeloma (3 papers, 2021 to 2025). "A higher expression of the aminopeptidase genes XPNPEP1, RNPEP, DPP3, and BLMH in multiple myeloma plasma cells was associated with shorter patient overall survival." (PMID 33810334, 2021).
septic shock (3 papers, 2022 to 2025). Shock caused by infection; frequently caused by gram negative bacteria, although some cases have been caused by other bacteria, viruses, fungi, and protozoa; characterized by fever, chills, tachycardia, tachypnea, and hypotension. "Circulating dipeptidyl peptidase 3 (cDPP3), a protease involved in the degradation of several cardiovascular mediators, represents another biological pathway strongly associated with outcome in septic shock, although unrelated to ADM." (PMID 36530868, 2022). "In an experimental septic shock model, the inhibition of circulating DPP3 by an anti-DPP3 antibody reduced catecholamine exposure and myocardial injury." (PMID 40993326, 2025).
colon cancer (2 papers, 2023). "In agreement to this, DPP3 was shown to be involved in cell cycle regulation and promoting malignant properties in colon cancer cells by involving CDK1." (PMID 37531267, 2023).
influenza (2 papers, 2012 to 2017). An acute viral infection of the respiratory tract, occurring in isolated cases, in epidemics, or in pandemics; it is caused by serologically different strains of viruses (influenzaviruses) designated A, B, and C, has a 3-day incubation period, and usually lasts for 3 to 10 days. "However, A549 cells treated with siRNAs targeting ADAMTS7 and DPP3, a gene not predicted to be involved in the NF-κB pathway, resulted in complete abrogation of NF-κB regardless of influenza infection." (PMID 22606348, 2012).
neuroblastoma (2 papers, 2020 to 2023). Neuroblastoma (NB) is the most common solid, extracranial childhood tumor. "In agreement with this, a previous study that first described the role of DPP3 in modulating NRF2 response in neuroblastoma cells also demonstrated NQO1 as a target of this mechanism." (PMID 37531267, 2023). "It has been reported that overexpression of DPP3 could potently activate the ARE in neuroblastoma cells (IMR-32 cells), leading to increased expression levels of NAD(P)H:quinone oxidoreductase 1 (NQO1), a phase II detoxifying enzyme regulated by ARE." (PMID 32546481, 2020).
postmenopausal osteoporosis (2 papers, 2020 to 2022). Metabolic disorder associated with fractures of the femoral neck, vertebrae, and distal forearm. "We aimed to assess the association of Dpp3 activity with bone fragility in postmenopausal osteoporosis and the impact of denosumab on enzymatic activity." (PMID 35745051, 2022). "Lack of DPP3 was found to augment bone loss caused by estrogen deprivation in the ovariectomized mouse model of human postmenopausal osteoporosis." (PMID 32546481, 2020).
bowel cancer (1 paper, 2024). "It has been shown that overexpressed DPP3 protein is associated with poor prognosis in patients with bowel cancer." (PMID 38655619, 2024). "In recent years, emerging studies have revealed that DPP3 is upregulated in aggressive brain glioma, ovarian cancer, endometrial cancer, and bowel cancer." (PMID 38655619, 2024).
chronic heart failure (1 paper, 2022). "Although the specific mechanism of DPP3 protection against chronic heart failure is still unclear, these results suggest that DPP3 may be a potential therapeutic target for cardiovascular diseases." (PMID 36312232, 2022).
endothelial dysfunction (1 paper, 2023). In vascular diseases, endothelial dysfunction is a systemic pathological state of the endothelium (the inner lining of blood vessels) and can be broadly defined as an imbalance between vasodilating and vasoconstricting substances produced by (or acting on) the endothelium. "This elevation could be explained by a decrease in ACE activity, due to endothelial dysfunction, or by the rapid degradation of Ang II due to endogenous peptidases, such as dipeptidyl peptidase 3 (DPP-3)." (PMID 36915144, 2023).
esophageal tumor (1 paper, 2023). "Furthermore, another dataset GSE29001 that utilized microdissected tissues for gene expression profiling also suggested that esophageal tumor tissues exhibit higher expression of DPP3 compared with the normal basal and differentiated epithelium." (PMID 37531267, 2023).
gastric cancer (1 paper, 2021). A primary or metastatic malignant neoplasm involving the stomach. "Among the identified DEGs, we found that 7 genes (IGFBP7, LOX, NRP1, PRSS3, DPP3, EFNA3, and CD73) were also differentially expressed in tumor tissues and associated with a poor or better prognosis in patients with gastric cancer." (PMID 34659527, 2021).
glioblastoma (1 paper, 2023). The most malignant astrocytic tumor (WHO grade IV). "We previously reported that an ETS transcription factor-binding motif is critical for the transcriptional regulation of DPP3 in glioblastoma cells." (PMID 37531267, 2023).
glioma (1 paper, 2023). A benign or malignant brain and spinal cord tumor that arises from glial cells (astrocytes, oligodendrocytes, ependymal cells). "In the context of its observed association with nervous system-related genes, aberrant DPP3 expression has been previously reported in glioma." (PMID 37531267, 2023).
leishmaniasis (1 paper, 2018). Infectious disease that is transmitted through the bite of hematophagous female phlebotomine sand flies. "In conclusion, the L. braziliensis DPP3 enzyme has been characterized and the recombinant protein could be used to search specific inhibitors that eventually would represent drugs for the treatment of leishmaniasis." (PMID 29304092, 2018).
leukemia (1 paper, 2021). A malignant (clonal) hematologic disorder, involving hematopoietic stem cells and characterized by the presence of primitive or atypical myeloid or lymphoid cells in the bone marrow and the blood. "DPP3 was reported to regulate the genesis of leukemia and other malignancies." (PMID 34359286, 2021).
lung adenocarcinoma (1 paper, 2019). A carcinoma that arises from the lung and is characterized by the presence of malignant glandular epithelial cells. "Also, Hast and coworkers reported that the protein dipeptidyl peptidase 3 (DPP3) can promote NRF2 stabilization by sequestering KEAP1 in HEK293T and lung adenocarcinoma H2228 cells." (PMID 31097977, 2019).
lung squamous cell carcinoma (1 paper, 2023). "Similarly, a positive correlation between the genomic copy number of DPP3 and its mRNA expression has been demonstrated in lung squamous cell carcinoma, indicating that gene amplification mediated overexpression of DPP3 is common in malignancies." (PMID 37531267, 2023).
osteoporosis (1 paper, 2022). A condition of reduced bone mass, with decreased cortical thickness and a decrease in the number and size of the trabeculae of cancellous bone (but normal chemical composition), resulting in increased fracture incidence. "To answer this question, we measured serum Dpp3 activity in a cohort of postmenopausal women with severe osteoporosis." (PMID 35745051, 2022). "Moreover, we found a positive correlation between FN-BMD and Dpp3 activity in severe osteoporosis; this is relevant since it has been well demonstrated that FN-BMD is the most accurate DXA parameter to estimate the fracture risk." (PMID 35745051, 2022). "In addition, the absence of correlation with age in the patients, compared with the controls, suggested that osteoporosis owing to estrogen withdrawal had a greater effect on Dpp3 activity, compared with the impact of aging." (PMID 35745051, 2022).
Polydipsia (1 paper, 2020). Excessive thirst manifested by excessive fluid intake. "Under these conditions, water intake of DPP3−/− mice was ∼4-fold higher as compared to DPP3+/+ mice, suggesting that DPP3 deficiency is associated with polydipsia in male animals." (PMID 32546481, 2020).
Wilms tumor (1 paper, 2021). An embryonal neoplasm characterized by the presence of epithelial, mesenchymal, and blastema components. "The second mechanism, commonly identified as “non-canonical pathway”, includes a number of different proteins such as p62, p21, dipeptidyl peptidase III (DPP3), PALB2, BRCA1, and Wilms tumor gene on the X chromosome (WTX)." (PMID 33918986, 2021).